WNT9B (Wnt family member 9B)
Description:
Ligand for members of the frizzled family of seven transmembrane receptors (Probable). Functions in the canonical Wnt/beta-catenin signaling pathway. Required for normal embryonic kidney development, and for normal development of the urogenital tract, including uterus and part of the oviduct and the upper vagina in females, and epididymis and vas deferens in males. Activates a signaling cascade in the metanephric mesenchyme that induces tubulogenesis. Acts upstream of WNT4 in the signaling pathways that mediate development of kidney tubules and the Muellerian ducts. Plays a role in cranofacial development and is required for normal fusion of the palate during embryonic development (By similarity).
Synonyms: WNT14B; WNT15
Tractability: Antibody: UniProt places it where antibodies can reach, with high confidence; its Gene Ontology location is reachable by antibodies, with high confidence; UniProt predicts a signal peptide or a membrane-spanning region.
Gene: Protein-coding gene on chromosome 17 (46,833,201 to 46,886,730, forward strand). Ensembl gene ENSG00000158955.
Subcellular location: Secreted, extracellular space, extracellular matrix; Secreted
Subcellular location (Human Protein Atlas): Vesicles; Predicted to be secreted
Pathways (Reactome):
Signal Transduction: Class B/2 (Secretin family receptors); WNT ligand biogenesis and trafficking
Developmental Biology: Nephron development
Gene Ontology:
Molecular function: receptor ligand activity; cytokine activity; frizzled binding; co-receptor binding; signaling receptor binding
Biological process: canonical Wnt signaling pathway; midbrain dopaminergic neuron differentiation; negative regulation of stem cell population maintenance; non-canonical Wnt signaling pathway; cell fate commitment; cellular response to retinoic acid; cornea development in camera-type eye; neuron differentiation; response to retinoic acid; Wnt signaling pathway
Cellular component: extracellular region
Genetic constraint (gnomAD): Loss-of-function variants: 12 observed, 28.45 expected, observed/expected ratio (o/e) 0.42, 90% interval 0.27 to 0.68. The upper end of that interval is the gene's LOEUF score, 0.68, which puts it in group 2 of 6, group 1 being the genes least tolerant of losing a copy. Missense variants: 442 observed, 482.29 expected, observed/expected ratio (o/e) 0.92, 90% interval 0.85 to 0.99. Synonymous variants: 218 observed, 215.77 expected, observed/expected ratio (o/e) 1.01, 90% interval 0.9 to 1.13.
Homologues: Orthologues: chimpanzee WNT9B (94% identical), pig WNT9B (94% identical), macaque WNT9B (93% identical), guinea pig WNT9B (92% identical), mouse Wnt9b (91% identical), dog WNT9B (90% identical), rabbit WNT9B (89% identical), rat Wnt9b (81% identical), zebrafish wnt9b (67% identical), tropical clawed frog wnt9b (52% identical), Drosophila melanogaster Wnt5 (37% identical), Caenorhabditis elegans cwn-2 (33% identical), and 4 more. Paralogues in human: WNT9A (60% identical), WNT2B (39% identical), WNT16 (37% identical), WNT2 (37% identical), WNT10B (36% identical), WNT4 (36% identical), WNT6 (36% identical), WNT1 (35% identical), WNT11 (34% identical), WNT5A (34% identical), WNT10A (34% identical), WNT7A (34% identical), and 6 more.